RN7SL280P (RNA, 7SL, cytoplasmic 280, pseudogene)
Gene: Miscellaneous RNA gene on chromosome 22 (21,722,895 to 21,723,182, reverse strand). Ensembl gene ENSG00000244671.
Homologues: Orthologues: chimpanzee Metazoa_SRP (96% identical). Paralogues in human: RN7SL2 (85% identical), RN7SL1 (84% identical), RN7SL3 (83% identical), RN7SL296P (81% identical), RN7SL357P (80% identical), RN7SL492P (80% identical), RN7SL147P (80% identical), RN7SL177P (80% identical), RN7SL712P (80% identical), RN7SL300P (80% identical), RN7SL398P (80% identical), RN7SL480P (80% identical), and 703 more.